VWF (von Willebrand factor)
Diseases named in the same sentence as VWF in open-access papers (continued):
Sharing a sentence is not in itself a finding about the gene and the disease.
hemophilia A (continued). "Human factor VIII (FVIII) functions as a cofactor for activated factor IX, and mutations in the FVIII gene (F8) result in hemophilia A. FVIII in plasma is proteolyzed and/or pinocytosed unless it is protected by non-covalent binding to soluble forms of von Willebrand factor (VWF) multimers." (PMID 26473492, 2015). "Our data suggest that the potential of FVIII co-storage with VWF is not affected in mild/moderate hemophilia A caused by reduced FVIII/VWF interaction in the circulation." (PMID 21909383, 2011). "Assuming that co-expression and co-storage of FVIII and VWF does occur in vivo, our data provide a molecular explanation for the fact that hemophilia A patients suffering from impaired complex assembly of FVIII and VWF in the circulation can be effectively treated with DDAVP." (PMID 21909383, 2011). "Furthermore, R2304C, which is linked to moderate cases of hemophilia A and high inhibitor titer levels, has been proposed to destabilize fVIII without disrupting vWf and phospholipid binding." (PMID 34177966, 2021). "Clinical data showing parallel increases in plasma FVIII and VWF levels in mild hemophilia A patients and Type 1 VWD patients following des-amino-D-arginine vasopressin (DDAVP) administration has lead to speculation that FVIII, in addition to VWF, is stored within human ECs." (PMID 26473492, 2015). "Cryoprecipitate, a preparation of plasma first developed for hemophilia A in the 1950s, typically contains significantly higher concentrations of fibrinogen, factor VIII, factor XIII, and von Willebrand factor than FFP." (PMID 41234974, 2025). "If test findings are confirmed, hemophilia A and 2N VWD can be differentiated using either a VWF:FVIIIB assay or by genetic analysis of F8 and VWF genes, respectively." (PMID 37601016, 2023). "In plasmas from patients with severe hemophilia A (less than 1% of normal factor VIII activity), the addition of polyP65 increased the VWF:RCo, similar to its effect in plasmas chemically depleted of factor VIII." (PMID 36430595, 2022). "Nevertheless, several studies regarding FVIII:C/VWF:Ag ratio and FVIII:C were conducted to determine the possibility of screening tests for haemophilia A carriership." (PMID 35330010, 2022). "This study aimed to determine the validity of the optimal cut-off value of FVIII:C/VWF:Ag ratio and to compare the FVIII:C/VWF:Ag ratio and FVIII:C value as screening tests for haemophilia A carriers." (PMID 35330010, 2022). "[e.g. CFTR (Cystic Fibrosis), vWF(von Willebrand Factor), HAEMA (Haemophilia A), G6PD] or Primary (nucleotide sequence) and secondary (Protein sequence) database." (PMID 20300299, 2008). "Therefore, 2N VWD, reflecting low FVIII:C, needs to be distinguished from hemophilia A (also reflecting low FVIII:C), so that the correct therapy is applied (VWF replacement in 2N VWD; FVIII replacement in hemophilia A)." (PMID 37601016, 2023). "Even though the AUC of FVIII:C showed very good results, the AUC of the FVIII:C/VWF:Ag ratio was excellent; thus, the FVIII:C/VWF:Ag ratio rather than FVIII:C should be considered for the screening of haemophilia A carriers." (PMID 35330010, 2022). "Activity of FVIII (FVIII:C) shows a low value in hemophilia A, sometimes in carriers also, and the ratio of FVIII:C to vWF:Ag is below the cut off value (i.e., below 0.6) in these individuals, similarly to that of vWD 2N patients." (PMID 33807613, 2021). "In particular, hemophilia A patients carrying a Tyr1680Phe, Ser2119Tyr, Arg2150His replacement or deletion of Ala2201, respond to DDAVP treatment by a concomitant increase of FVIII and VWF." (PMID 21909383, 2011). "Using the VWF Ristocetin Cofactor assay, the most accepted method for studying VWF in platelet adhesion, we found that polyP activates this role of VWF only at low levels of FVIII, such as in plasmas with chemically depleted FVIII and plasmas from severe hemophilia A patients." (PMID 36430595, 2022).
hemophilia A (continued). "On the contrary, in plasmas from patients with moderate hemophilia A (with 1 to 20% of factor VIII activity in the blood), the addition of polyP did not significantly change the VWF:RCo activity." (PMID 36430595, 2022). "Since hemophilia A patients would not be deficient in vWF, the vWFnullFVIIInull strain can be used in a special situation to evaluate the factor VIII pharmacokinetics in the absence of vWF, which is especially valuable when engineered factor VIII may have altered interaction with vWF." (PMID 25401041, 2013). "In addition, hemophilia A dogs (i.e., no detectable F.VIII but normal VWF) form occlusive arterial thrombosis as readily as normal dogs using the same experimental model." (PMID 22091368, 2010).
Hypertension (62 papers, 2008 to 2026). The presence of chronic increased pressure in the systemic arterial system. "The study also showed an association between patients with arterial hypertension and dyslipidemia and an increased expression of vWF/CTNNB-1 (p = 0.049/p = 0.023) and IL-6/GJA-1 (p = 0.034/p = 0.004), respectively." (PMID 36992415, 2023). "vWF is a biomarker for endothelial damage, and an increase in its level is associated with hypertension and cardiovascular disease." (PMID 35111278, 2022). "We did not observe any significant difference in LDL-EV VWF in patients with and without hypertension despite previous studies reporting such associations for plasma VWF levels and hypertension." (PMID 36613770, 2022). "Hypertension is also associated with increased VWF concentrations, and the O-group is associated with higher rates of hypertension." (PMID 34419051, 2021). "Since hypertension is linked to an increase in thrombogenic potential, we hypothesized that it might also be associated with a shift in distribution towards larger, more thrombogenic vWF multimers." (PMID 26290867, 2015). "Many factors could cause activation of the hemostatic system in hypertension and the present study demonstrates that even minor differences in regulation of cortisol secretion are associated with a prothrombotic state as defined by higher levels of D-dimer, F1 + 2, and vWF." (PMID 38836224, 2024). "αIIbβ3 expressions to healthy levels, but also lowered VWF and P-selectin levels that were unaffected by hypertension." (PMID 39433750, 2024). "Serum levels of FGF21 and vWF are increased in elderly patients with hypertension and comorbid CAS, so they can be used for diagnosing CAS and predicting prognosis." (PMID 35242298, 2022). "Several researchers have reported that plasma VWF increases not only in patients with hypertension and arteriosclerosis but also in healthy individuals with aging." (PMID 36137144, 2022). "Chronic CBD treatment decreased and increased the intensity of vWF and eNOS staining, respectively, in aortas and mesenteric G3 arteries in the normotensive and hypertensive groups for both models of hypertension." (PMID 34832902, 2021). "Our previous study reported sFlt-1 level elevated in IgAN patients and also correlated with proteinuria, hypertension and vWF level." (PMID 32790760, 2020). "The expression of vWF in renal glomeruli has been reported in patients with hypertension or vascular disease." (PMID 32604873, 2020). "Plasma sFlt-1 levels were significantly elevated in IgAN patients and correlated with proteinuria, hypertension and vWF levels." (PMID 32790760, 2020). "Increased fluid shear stress can induce WP body degranulation and it is therefore possible that endothelial cells exposed to high shear stress during hypertension release this vWF into the vascular lumen." (PMID 26290867, 2015). "Accordingly, increased plasma levels of vWF have been reported for patients with stage 2 hypertension (≥160/≥100 mmHg)." (PMID 26290867, 2015). "It is noteworthy however that severe hypertension is typically managed with blood-pressure lowering medications and that this affects vWF profile." (PMID 26290867, 2015). "It is possible that higher doses of LC n-3 PUFAs are required to modulate vWF in this population or that patients with more advanced hypertensive disease are required to see an effect." (PMID 26290867, 2015). "Correlations of sFlt-1 with hypertension, proteinuria, Oxford-E score and plasma vWF were further evaluated in the combined 205 patients with IgAN." (PMID 25007257, 2014). "In conclusion, the present study found elevated sFlt-1 in IgAN patients for the first time and further identified its correlation with proteinuria, hypertension and vWF levels." (PMID 25007257, 2014). "The present study found elevated sFlt-1 in IgAN patients and further identified its correlation with proteinuria, hypertension and vWF levels." (PMID 25007257, 2014).
Hypertension (continued). "We included proteinuria, hypertension, histological E scores and plasma vWF levels as parameters to evaluate endothelial injury in the present study." (PMID 25007257, 2014). "We further explored the correlations of elevated sFlt-1 with proteinuria, hypertension, Oxford-E scores and vWF levels." (PMID 25007257, 2014). "Our present study observed elevated vWF levels in patients with IgAN, which also correlated with clinical proteinuria and hypertension in IgAN and confirmed the existence of endothelial injury in IgAN." (PMID 25007257, 2014). "Moreover, immunofluorescence showed that hypertension significantly lowered the expression of vascular endothelial cell marker vWF, a trend reversed under both cSVF and tSVF treatments." (PMID 41551933, 2026). "Hypertension and elevated vWF: Ag levels remained independent in multivariate analysis." (PMID 41085687, 2025). "Elevated serum PAI-1, endothelin, von Willebrand factor, and oxidative stress may trigger mechanisms linking MA and SA, and the male rats with spontaneous hypertension related much of the pro-atherosclerotic markers with MA than female rats." (PMID 36227142, 2022). "The effect of mild hypertension on vWF levels is controversial." (PMID 26290867, 2015). "Endothelial injury, which may present clinically as hypertension, proteinuria and increased von Willebrand Factor (vWF) level, is a common manifestation in IgA nephropathy (IgAN)." (PMID 25007257, 2014). "Furthermore, correlations between vWF and proteinuria, hypertension, and Oxford-E score were also analyzed." (PMID 25007257, 2014). "Elevated levels of vWF, sE-selectin, and sPselectin may develop as a result of endothelial damage mediated by hypertension." (PMID 22593709, 2012). "In this study, we determined the plasma concentration, multimer distribution, and collagen binding activity of vWF in subjects with mild hypertension and determined whether these parameters might improve after dietary supplementation with moderate amounts of LC n-3 PUFAs." (PMID 26290867, 2015). "This study aimed to investigate the relationship between serum FGF21 and vWF expression and carotid atherosclerosis (CAS) in elderly patients with hypertension." (PMID 35242298, 2022). "Although change in vWF concentration and change in vWF multimer profile were similar across treatment groups and intragroup variability was very small, it might be of interest in future studies to investigate larger cohorts of subjects or a population of subjects with more severe hypertension." (PMID 26290867, 2015). "The high prevalence of hypertension, frequently observed TMA and elevated circulating vWF indicate vascular endothelial injury in IgAN." (PMID 25007257, 2014). "The relationship between serum FGF21 and vWF expression and CAS in elderly patients with hypertension remains unclear." (PMID 35242298, 2022). "It is possible that patients with O blood group and hypertension have similar VWF levels as patients with AB blood group and no hypertension, and that further increases in VWF in AB/hypertensive cases are limited." (PMID 34419051, 2021). "This included lower levels of insulin, glycated hemoglobin, blood glucose, inflammatory markers (IL-6 and CRP), and hemostatic factors (von Willebrand factor, factor VIII, tPA antigen, and D-dimer); a smaller waist circumference; and higher lung function and reduced odds of hypertension." (PMID 30124747, 2018). "The capacity of mild (stage 1) hypertension (140–159/90–99 mmHg) to modulate vWF levels is inconclusive, with an increase in vWF concentration reported by some, but not by others." (PMID 26290867, 2015). "The associations between increasing age, hypertension, and BG PVS count and volume may not have been completely corrected statistically and may confound the association of PVS and vWF, both of which normally rise with age." (PMID 27576214, 2016).
Hypertension (continued). "Increased plasma concentration of von Willebrand factor (vWF), a procoagulant glycoprotein, has been identified in patients with severe hypertension, with some, but not all studies showing an increase with mild hypertension." (PMID 26290867, 2015). "We report here that subjects with mild hypertension did not present with higher plasma vWF levels." (PMID 26290867, 2015). "Whilst one study reported an increase of vWF in patients with mild hypertension, another did not." (PMID 26290867, 2015). "Besides, this study did not investigate various targeted treatments for hypertension, so the effects of these treatments on FGF21 and vWF levels are unclear." (PMID 35242298, 2022).
Arterial thrombosis (54 papers, 2010 to 2025). The formation of a blood clot inside an artery. "Elevated levels of the plasma glycoprotein von Willebrand factor (VWF) are associated with an increased risk of developing arterial thrombosis and atherothrombosis." (PMID 40093962, 2025). "Elevated von Willebrand factor (vWF) levels suggest endothelial injury, and are associated with cisplatin-induced arterial thrombosis." (PMID 39810847, 2024). "As a results, higher VWF levels are associated with (unprovoked) venous thromboembolism and arterial thrombosis." (PMID 39726607, 2024). "Studies have shown that aPLs antibodies present in APS patients are able to increase the risk of arterial thrombosis by upregulating the plasma levels of active VWF and by promoting platelet activation." (PMID 33919627, 2021). "To conclude, aPLs antibodies present in APS patients are able to increase the risk for arterial thrombosis by upregulating the plasma levels of active VWF and by promoting platelet activation." (PMID 33919627, 2021). "This is important for dose-finding and translation of data from healthy subjects to patients with elevated VWF levels and lays the foundation for defining and predicting dose ranges in patients at risk for arterial thrombosis." (PMID 32636459, 2020). "In the context of arterial thrombosis with coronary syndromes, pathologically high shear flows cause VWF to spontaneously form dense and massive VWF fibers." (PMID 30083534, 2018). "Since VWF is a risk factor for arterial thrombosis, it is of great interest to discover determinants of VWF response to physical stress." (PMID 24626470, 2014). "It has been speculated that cisplatin may enhance tissue factor activity and platelet activation and elevate the von Willebrand factor, which can cause endothelial injury and potentiate arterial thrombosis." (PMID 39944600, 2025). "In previous literature, miR-103a-3p has known targets with VWF, miR-145-5p is associated with arterial thrombosis and smooth muscle proliferation, as well as ADAMTS13 levels, and miR-27b-3p, miR-320a/b-3p, and miR-424-5p are associated with venous thromboembolism." (PMID 39237986, 2024). "Several studies showed the association of high blood VWF levels with arterial thrombosis." (PMID 35215805, 2022). "In the pathologic process, vWF is deemed to be a risk factor for arterial thrombosis." (PMID 31450612, 2019). "Given the known importance of vWF in high‐shear arterial thrombosis, we investigated the role of vWF–GPIbα interaction in our vortex‐induced platelet aggregation model." (PMID 40468616, 2025). "High shear arterial thrombosis involves mainly von Willebrand Factor (VWF)-dependent platelet cross-linking." (PMID 38212360, 2024). "Notably, rHDL particles may also positively impact thrombosis as they have been shown to inhibit microvascular and arterial thrombosis by preventing the self-association of von Willebrand factor (VWF), which is crucial for platelet adhesion and aggregation under high shear stress conditions." (PMID 39057711, 2024). "The release of thrombosis factors such as von Willebrand factor (vWF) and P-selectin plays a crucial role in AS and arterial thrombosis." (PMID 37754811, 2023). "The abnormal elevation of VWF, a glycoprotein mainly synthesized by endothelial cells and involved in arterial thrombosis, suggests a functional disturbance in the ability of endothelial cells to participate in coagulation and fibrinolysis." (PMID 37188751, 2023). "The von Willebrand factor (VWF) plays an important role in the control of hemostasis and the onset of pathological arterial thrombosis." (PMID 35216161, 2022). "In atherosclerotic lesions, VWF can act as a bridge between collagen and platelets, as well as between platelets themselves, thereby being a major contributor to the development of arterial thrombosis." (PMID 33919627, 2021).